MOB1A (MOB kinase activator 1A)
Description:
Activator of LATS1/2 in the Hippo signaling pathway which plays a pivotal role in organ size control and tumor suppression by restricting proliferation and promoting apoptosis. The core of this pathway is composed of a kinase cascade wherein STK3/MST2 and STK4/MST1, in complex with its regulatory protein SAV1, phosphorylates and activates LATS1/2 in complex with its regulatory protein MOB1, which in turn phosphorylates and inactivates YAP1 oncoprotein and WWTR1/TAZ. Phosphorylation of YAP1 by LATS1/2 inhibits its translocation into the nucleus to regulate cellular genes important for cell proliferation, cell death, and cell migration. Stimulates the kinase activity of STK38 and STK38L. Acts cooperatively with STK3/MST2 to activate STK38.
Synonyms: C2orf6; MOB4B; MOBK1B; MOBKL1B; FLJ10788; MOB1; FLJ11595; Mats1; MABKL1B
Tractability: Small molecule: a structure with a bound ligand is known. PROTAC: ubiquitination databases record sites on it; its protein half-life has been measured.
Gene: Protein-coding gene on chromosome 2 (74,152,528 to 74,178,932, reverse strand). Ensembl gene ENSG00000114978.
Subcellular location (Human Protein Atlas): Nucleoli; Cytosol; Nucleoplasm
Pathways (Reactome):
Signal Transduction: Signaling by Hippo
Gene Ontology:
Molecular function: protein binding; protein serine/threonine kinase activator activity; protein kinase activator activity
Biological process: hippo signaling
Cellular component: cytoplasm; extracellular exosome; cytosol
Genetic constraint (gnomAD): Loss-of-function variants: 5 observed, 13.04 expected, observed/expected ratio (o/e) 0.38, 90% interval 0.2 to 0.81. The upper end of that interval is the gene's LOEUF score, 0.81, which puts it in group 3 of 6, group 1 being the genes least tolerant of losing a copy. Missense variants: 112 observed, 166.55 expected, observed/expected ratio (o/e) 0.67, 90% interval 0.58 to 0.79. Synonymous variants: 57 observed, 55.14 expected, observed/expected ratio (o/e) 1.03, 90% interval 0.83 to 1.29.
Homologues: Orthologues: guinea pig MOB1A (100% identical), macaque MOBKL1B (100% identical), mouse Mob1a (100% identical), pig MOB1A (100% identical), rabbit MOB1A (100% identical), dog MOB1A (99% identical), rat Mob1a (99% identical), rat Mob1a-ps1 (99% identical), chimpanzee MOB1A (98% identical), tropical clawed frog mob1a (97% identical), zebrafish mob1a (96% identical), Drosophila melanogaster mats (86% identical). Paralogues in human: MOB1B (96% identical), MOB3B (53% identical), MOB3A (52% identical), MOB3C (50% identical), MOB2 (42% identical), MOB4 (22% identical).
Diseases named in the same sentence as MOB1A in open-access papers:
MOB1A is named in the same sentence as 22 diseases in open-access papers, as found by Europe PMC text mining. Sharing a sentence is not in itself a finding about the gene and the disease. The quoted sentences say what the papers report.
ovarian carcinoma (4 papers, 2022 to 2023). A malignant neoplasm originating from the surface ovarian epithelium. "It was demonstrated that MOB1A mRNA expression was significantly associated with reduced overall survival (OS) time in ovarian cancer." (PMID 35135596, 2022). "Our results demonstrated that MTHFD2 expression in ovarian cancer was up-regulated and associated with poor prognosis in ovarian cancer patients, which may play a role in malignant transformation mainly through MOB1A signaling pathway." (PMID 35135596, 2022). "MOB1A overexpression induces cell proliferation, migration, invasiveness, and cell cycle of ovarian carcinoma cells." (PMID 37314589, 2023). "Together, a detailed delineation of the molecular mechanism by which MOB1A modulates ovarian cancer development awaits future investigation." (PMID 37314589, 2023). "Overexpression of MOB1A has a positive effect on ovarian cancer progression and is likely involved in the regulation of the PI3K/AKT/mTOR signaling pathway." (PMID 37314589, 2023). "We also found that that MTHFD2 has a role in malignancy mainly through the MOB1A signaling, which is a potential target for treating ovarian cancer." (PMID 35135596, 2022). "These experiments preliminarily demonstrate that MTHFD2 exerted its effects on the malignant behaviors of ovarian cancer cells through the MOB1A signaling pathway." (PMID 35135596, 2022). "Then, we identified the expression of MOB1A in ovarian cancer through GEPIA database and our own samples." (PMID 35135596, 2022). "By mining co-expression and correlation analysis data, we determined that MTHFD2 and MOB1A were both upregulated in ovarian cancer." (PMID 35135596, 2022). "Consistently, after knock down MTHFD2, we found that the expression of MOB1A was significantly decreased in ovarian cancer cell lines." (PMID 35135596, 2022). "The results demonstrated that MOB1A mRNA expression was significantly up-regulated and correlated with poor survival in ovarian carcinoma samples compared with controls." (PMID 35135596, 2022). "Moreover, it has a role in malignancy mainly through the MOB1A signaling, which is a potential target for treating ovarian cancer." (PMID 37628752, 2023). "Furthermore, our own results demonstrated the over-expression of MOB1A mRNA and worse probabilities of survival in ovarian cancer." (PMID 35135596, 2022). "Finally, the expression of MOB1A was inhibited by MTHFD2 in ovarian cancer cells." (PMID 35135596, 2022). "While MOB1A and CCDC6 were significantly over-expressed in ovarian cancer samples, expression of these genes, as well as of TUBB, PRKAR1A, and SOCS3 appeared to be expressed at high levels in multiple healthy tissue sites." (PMID 36943460, 2023).
colorectal cancer (3 papers, 2022 to 2024). A primary or metastatic malignant neoplasm that affects the colon or rectum. "For example, a recent study has shown that WEE2-AS1, highly expressed in CAF-derived sEVs, targeted MOB1A, accelerated MOB1A degradation, inhibited the Hippo pathway, and promoted cancer cell proliferation in colorectal cancer." (PMID 39684264, 2024). "Dysregulation of MOB1A has been reported in several malignant tumors, including colorectal cancer, glioblastoma, intrahepatic cholangiocarcinoma, non-small cell lung cancer, and gallbladder carcinoma." (PMID 37314589, 2023). "However, MATS1 (also known as MOB1A) expression is decreased in tumor tissue and its low expression is connected with tumor progress, invasion, and metastasis of colorectal cancer." (PMID 37314589, 2023).
breast carcinoma (2 papers, 2020 to 2022). "Over-expression of circCCDC85A rescued miR-550a-5p-mediated promotion of the proliferative, migrative, and invasive abilities of breast cancer cells, and reversed miR-550a-5p-mediated downregulation of its target gene MOB1A." (PMID 34983617, 2022). "Consistently, we herein found that the enforced expression of MOB1A suppressed the proliferative, migrative, and invasive abilities of breast cancer cells." (PMID 34983617, 2022). "Mechanically, circCCDC85A may serve as a molecular sponge of miR-550a-5p and restore miR-550a-5p-mediated targeting repression of tumor suppressor gene MOB1A in breast cancer." (PMID 34983617, 2022). "Our data presented the inhibitory function of circCCDC85A in breast cancer and suggested that circCCDC85A may regulate tumor progression at least in part by competitively activating MOB1A by serving as a sponge platform for miR-550a-5p." (PMID 34983617, 2022). "We found that miR-550a-5p could reinforce the proliferative, migrative, and invasive abilities of breast cancer cells through directly targeting 3’UTR of the tumor suppressor MOB1A." (PMID 34983617, 2022). "Mechanically, circCCDC85A may serve as a molecular sponge of miR-550a-5p and restore miR-550a-5p-mediated targeting repression of the tumor suppressor gene MOB1A in breast cancer." (PMID 34983617, 2022). "In this study, MOB kinase activator 1A (MOB1A) was detected in stage 2, while both MOB1A and MOB1B were detected in stage 3 breast cancer samples." (PMID 31945087, 2020).
gallbladder carcinoma (2 papers, 2022). "Furthermore, multiple studies have revealed that MOB1A is involved in development and progress in many types of cancers, such as glioma, gallbladder carcinoma, cervical carcinoma, pancreatic ductal adenocarcinoma, and gastric cancer." (PMID 35135596, 2022).
tongue cancer (2 papers, 2023 to 2024). A malignant neoplasm affecting the tongue. "This genetically modified mouse strain develops tongue cancer upon tamoxifen exposure through the Cre-mediated excision of the floxed Mob1a gene." (PMID 38138101, 2023). "To do so, we depleted MOB1A/B in a tongue cancer-derived cell line CAL-27 and reconstituted the MOB1A/B DKO CAL-27 cells with wild-type MOB1A and MOB1B and their H161Y and H161D mutants." (PMID 39572544, 2024).
chordoma (1 paper, 2022). Chordomas are rare malignant tumors arising from embryonic remnants of the notochord in axial skeleton. "Five regulators of this pathway (TAOK1, TAOK2, MOB1A/B, and LATS1) were significantly suppressed in chordoma samples and two of them are predicted targets for upregulated miRNAs (TAOK1 for miR-142, and MOB1B for miR-148a and miR-182)." (PMID 36033338, 2022).
mental disorder (1 paper, 2023). A disease that has its basis in the disruption of mental process. "Notably, we identified significant associations for CLEC11A and MOB1A, genes known to be associated with immune and mental disorders." (PMID 37012247, 2023).
pancreatic carcinoma (1 paper, 2025). "The cytoplasmic immunolocalization of SAV1 and MOB1A is also in line with previous reports in pancreatic carcinoma for SAV1 and in NSCLC for MOB1A." (PMID 40649713, 2025).
teratoma (1 paper, 2019). A non-seminomatous germ cell tumor characterized by the presence of various tissues which correspond to the different germinal layers (endoderm, mesoderm, and ectoderm). "To identify whether Mob1a/b is required for spontaneous differentiation into tissues of the three germ layers in vivo, which is Yap-dependent, we performed teratoma formation assays." (PMID 31723125, 2019).
tumor (14 papers, 2013 to 2025). "A protein encoded by the MOB1A gene is a component of the Hippo signaling pathway, which promotes apoptosis and controls organ size and tumor growth." (PMID 37415732, 2023). "MOB1A plays a role in promoting the malignant biological behavior of tumor cells through PI3K/AKT/mTOR signaling pathway." (PMID 37314589, 2023). "The expression of MOB1A was positively correlated with the tumor stage and histological grade of OC patients." (PMID 37314589, 2023). "In mammals, genetic studies provided the same picture, namely that loss of MST1/2, MOB1A/B, or LATS1 results in tumour growth, while YAP overexpression is sufficient to induce tumours." (PMID 23985307, 2013). "MOB1A has shown intriguing role in limiting tumor progression as a part of Hippo signaling pathway." (PMID 36380816, 2023). "MOB1A is a mainly cytoplasmic protein and is known to control organ size and tumor growth." (PMID 37314589, 2023). "MOB1A reportedly functions as a tumor suppressor in several cancer types." (PMID 34983617, 2022). "Interestingly, other studies have shown that MOB1A can restrict the growth of cancer by activating the tumor-suppressing Hippo signaling pathway; this actually induced apoptosis in several cancer cell lines." (PMID 31945087, 2020). "In this study, the overexpression of MOB1A inhibited the autophagy activity of SKOV3 cells, which was accompanied by the enhancement of tumor cell proliferation and the promotion of the cell cycle." (PMID 37314589, 2023). "To explore the possible role of protein lactylation in driving tumor cell proliferation, we then focused on the Hippo signaling pathway, in which several components or regulatory proteins, such as ACTG1, MOB1A, PPP1CA, YAP, and TEAD1, were found to be lactylated." (PMID 38512451, 2024). "RAS bound with RASSF5, activate MST1/235,44 to form STK3/MST2 and STK4/MST1 complexes in the hippo signaling pathway that plays a crucial role in tumor suppression by limiting proliferation and stimulating apoptosis where SAV1, MOB1A/B act as effector molecules." (PMID 32884013, 2020).
cancer (10 papers, 2012 to 2024). A tumor composed of atypical neoplastic, often pleomorphic cells that invade other tissues. "In CRC, exosomes from cancer-associated fibroblasts (CAFs) transport lncRNA WEE2-AS1 to induce MOB kinase activator 1A (MOB1A) degradation and inhibit Hippo signaling pathway, thereby accelerating the growth of CRC cells." (PMID 36765913, 2023). "Mps One Binder Kinase Activator (MOB)1A, one of the most core components of the Hippo pathway, was considered to influence biological functions in various cancers." (PMID 35135596, 2022). "Six pDGVs in the PINX1, MOB1A, CLTCL1, PRR5, CCDC136, and TRIM32 genes involved the exact amino acid residues affected by known somatic cancer variants." (PMID 33273457, 2020). "In addition, the exact mechanism of MOB1A in cancer development remains to be elucidated." (PMID 37314589, 2023). "Since there is no antibody available to distinguish MOB1A and MOB1B, we analyzed their expressions by RT-PCR in a panel of pancreatic normal and cancer cells, which showed that MOB1A mRNA level is 5–15 fold higher than MOB1B in these cells." (PMID 31659153, 2019).
MOB1A also shares sentences with these, for which no sentence is quoted: cervical carcinoma (1 paper); cervical squamous cell carcinoma (1); chondrosarcoma (1); gastric cancer (1); glioma (1); head and neck squamous cell carcinoma (1); infection (1); melanoma (1); meningioma (1); pancreatic ductal adenocarcinoma (1); schwannoma (1).